AIM2 (absent in melanoma 2)
Diseases named in the same sentence as AIM2 in open-access papers (continued):
Sharing a sentence is not in itself a finding about the gene and the disease.
melanoma (continued). "The activation of the AIM2 (Absent in melanoma 2) inflammasome by self and foreign double-stranded DNA (dsDNA) mediates pyroptosis." (PMID 38343546, 2024). "The mechanisms and signaling pathways leading to the absent in melanoma 2 (Aim2) inflammasome activation have been elegantly elucidated using Francisella novicida as a model." (PMID 37266012, 2023). "Due to its lack of expression in melanoma, it is designated as absent in melanoma 2 (AIM2), belonging to a family of HIN-200 proteins." (PMID 36993972, 2023). "[Abbreviations—AIM2: absent in melanoma 2; MMT: macrophage-to-myofibroblast transition; NLRP: nucleotide-binding oligomerization domain, leucine-rich repeat-containing protein]." (PMID 35743263, 2022). "E199L has been reported to be a positive regulator of the NLRP3- (NLR Family Pyrin Domain Containing 3) and AIM2- (Absent in melanoma 2) inflammasome mediated inflammatory response." (PMID 35081156, 2022). "AIM2 gene plays the tumor-suppressive role in HPV-infected cervical cancer, breast cancer, squamous cell carcinoma; while AIM2 gene is regarded as a protective factor in melanoma and colorectal cancer." (PMID 36118867, 2022). "NLRP3 showed no changes in gene expression between control-RPE or AMD-RPE cells, while absent in melanoma 2 (AIM2) was 2.18-fold higher expressed in AMD-RPE cells when compared to control-RPE cells exposed to IL-1α priming and vehicle." (PMID 34202702, 2021). "The levels of nuclear enriched abundant transcript 1 (NEAT1), miR-485-5p, and absent in melanoma 2 (AIM2) in CD4+ T cells were determined using real-time quantitative polymerase chain reaction (RT-qPCR)." (PMID 34696702, 2021). "A single functional variant related to this pathway was observed in patient #16: a frameshift deletion in the Absent in melanoma 2 (AIM2) gene (ENTREZID: 9447; exon 5: c.712delA or p.T238Hfs*14; without rs ID; located on chr1 at 159062697 position)." (PMID 35004305, 2021). "An increase in AIM2 expression occurs in common melanocytic nevi and most primary melanomas, whereas AIM2 expression is generally low or even nonexistent in melanoma metastases." (PMID 34014039, 2021). "Inflammasome sensors include members of the NLR (nucleotide-binding domain and leucine-rich repeat containing) family (NLRP1, NLRP3, NAIP, and its adaptor NLRC4), AIM2 (Absent in Melanoma 2) and pyrin." (PMID 33138274, 2020). "To date, various inflammasomes, including NLRP1, NLRP2, NLRP3, absent in melanoma (AIM2) and NLRC4, have been identified." (PMID 31941010, 2020). "Pattern recognition receptors involved in inflammasomes comprise nucleotide-binding oligomerization domain and leucine-rich repeat-containing receptors (NLR) such as NLRP3 and NAIP, as well as absent in melanoma-2 (AIM-2)." (PMID 32431703, 2020). "Here, we developed the CAIX promotor (CAIXpromotor)‐controlled CRAd armed with a tumour suppressor absent in melanoma 2 (AIM2) to enhance its oncolytic potency." (PMID 32725966, 2020). "Other tested DNA sensors (Cgas, Sting, Ddx41, Dhx9, Dhx36, Lrrfip1, Mre11, and additionally Aim2, which is absent in melanoma cells) were expressed in macrophages but were not significantly upregulated after irradiation." (PMID 33202881, 2020). "The expression levels of nucleic acid sensors interferon gamma-inducible protein 16 (IFI16) and absent in melanoma 2 (AIM2) in peripheral blood mononuclear cell (PBMC) and skin from AOSD patients and HCs were analyzed by PCR and immunohistochemistry." (PMID 31068953, 2019). "We found that some inflammasome genes, including CARD domain containing 4 (NLRC4), caspase 5 (CASP5), absent in melanoma 2 (AIM2) and the already mentioned NLRP3, were upregulated in our data." (PMID 30935390, 2019). "Accordingly, analysis of anti-PD-1-treated melanoma patients suggested that NLRP6, NLRP7, AIM2, and NLRC4 inflammasomes might contribute to antitumor responses unleashed by checkpoint blockers." (PMID 31085177, 2019).
melanoma (continued). "S. mutans induced IL-1β secretion via caspase-1 activation, and S. mutans-induced IL-1β secretion required absent in melanoma (AIM2), NLR family pyrin domain-containing 3 (NLRP3) and NLR family CARD domain-containing 4 (NLRC4) inflammasome activation." (PMID 30078841, 2018). "These cytokines induce multiprotein complexes termed ‘inflammasomes’ such as nucleotide oligomerization domain (NOD)-like receptors (NLRs) and absent in melanoma (AIM2)." (PMID 30042341, 2018). "So far, different inflammasomes have been identified, including nucleotide-binding oligomerization domain-like receptors (NLRs) and absent in melanoma 2 (AIM2)." (PMID 28182085, 2017). "As control served the double-stranded DNA mimic dAdT that signals NLRP3 independently via the DNA sensor absent in melanoma 2 (AIM2), still requiring the adapter molecule ASC as well as caspase-1 for the processing of IL-1β." (PMID 29403480, 2017). "Absent in melanoma (AIM2) is a member of the interferon-inducible HIN-200 protein family and is recently recognized to play an important dual role in both innate immunity and tumor pathology." (PMID 27167192, 2016). "We also present additional phenotyping data with dietary manipulation and initial expression data for two BMD candidate genes, absent in melanoma 2 (Aim2) and AC084073.22." (PMID 20687154, 2011). "The presence of viral RNA or DNA in cytosol is detected by retinoic acid inducible gene-I (RIG-I) and melanoma differentiation-associated gene 5 (MDA-5), DNA-dependent activator of IFN-regulator factors (DAI) or absent in melanoma 2 (AIM2)." (PMID 20492658, 2010). "Our results on elevated neutrophil velocities in ET are completely in line with the hypothesis that JAK V617F can trigger the Aim2 (absent in melanoma 2) inflammasome and lead to IL-1β generation." (PMID 41465385, 2025). "In a mouse model of VCID, CCH activates NOD-like receptor family, pyrin domain containing 3 (NLRP3), absent in melanoma 2 (AIM2) inflammasome in reactive astrocytes in white matter tracts in mouse brain, as shown by higher numbers of AIM2 and NLRP3 in GFAP+ cells at 4 weeks after BCAS procedure." (PMID 38659577, 2024). "However, some studies suggest that SARS-CoV-2 infection is associated with other inflammasomes as well; such as NLRP1, absent in melanoma-2 (AIM-2), caspase-4 and -8 which were mostly found during dsRNA virus or bacteria infection." (PMID 37360532, 2023). "The immune and inflammatory response node contained 99 proteins and genes directly involved in the immune response such as interleukins and chemokines; T lymphocyte markers such as CD96, TLR8, CD80; or CCR5, beta-2-microglobulin (B2M) or absent in melanoma 2 (AIM2)." (PMID 37686682, 2023). "A member of the interferon-inducible HIN-200 protein family is absent in melanoma 2 (AIM2)." (PMID 37008939, 2023). "Decreased expression of AIM2 (absent in melanoma 2) was first found in melanoma." (PMID 36163033, 2022). "The other two inflammasome-assembling PRRs are AIM2 (absent in melanoma 2) and pyrin." (PMID 35743263, 2022). "However, this then causes the HAdV double-stranded DNA genome to become accessible to AIM2 (absent in melanoma 2) and in turn to initiate inflammasome formation." (PMID 34093588, 2021). "It has been recently shown that different Gram-negative OMVs may vehicle bacterial DNA to host cytosol and trigger AIM2 (Absent in Melanoma 2) dependent inflammasomes." (PMID 32973778, 2020). "However, most of the evidence comes from numerous studies on the PYHIN protein AIM2 (Absent In Melanoma 2), a cytoplasmic sensor of double-stranded DNAs." (PMID 33353088, 2020). "In consent with previous studies that have highlighted the role of AIM2 (absent in melanoma 2) and ALOX-5 (arachidonate 5-lipoxygenase) genes in RA pathogenesis, our study also demonstrated the enhanced expression of these genes in RA patients as compared to HCs." (PMID 28210261, 2017).
melanoma (continued). "Of note, additional studies have indicated that not only NLRP3, but also NLRP1, NLRC4 [NLR (Nod-like receptor) family CARD-containing 4] and AIM2 (absent in melanoma 2) form the inflammasomes that drive inflammation in response to a wide variety of molecular patterns." (PMID 22701621, 2012). "Therefore, we first measured the mRNA expression of DNA-dependent activator of IFN-regulatory factors (DAI) and absent in melanoma 2 (AIM2), which recognize cytosolic dsDNA using real-time PCR." (PMID 22550608, 2012). "This paradox may be due to intentional sun avoidance in these patients or increased AIM2 (Absent in Melanoma 2) protein levels, which have tumour-suppressive effects in cancers such as melanoma, breast and prostate, but may increase risk in others like lung cancer." (PMID 40943714, 2025). "Moreover, a nucleotide-binding oligomerization domain-like receptor (NLR) protein is the main component of inflammasomes and is classified into four types: NLRP1/NALP1b inflammasome, NLRC4/IPAF inflammasome, NLRP3/NALP3 inflammasome, and AIM2 (absent in melanoma 2) containing inflammasome." (PMID 34067673, 2021). "B16F10 mouse melanoma cells, which do not express pro-IL-1β, NLRP3 and AIM2 (data not shown), were chosen to generate B16F10-IL-1β, B16F10-pro-IL-1β (expressing non-secretable IL-1β) and B16F10-vector cells." (PMID 23065753, 2012). "In contrast, the improved survivals seen with high AIM2 and high NLRC4 were retained in patients with high or low TILs score suggesting the beneficial effect might be intrinsic to melanoma cells and independent of TILs level." (PMID 32027447, 2020). "Absent in melanoma 2 (AIM2), discovered in melanoma in 1997,1 was originally described as a novel member of interferon (IFN)‐inducible PYHIN proteins, which contains four members in humans (AIM2, IFI16, IFIX, and MNDA) and 13 homologous proteins (e.g., Aim2, p202, p204, and p205) in mice." (PMID 34014039, 2021).
viral infection (56 papers, 2010 to 2025). "In addition, certain viral infections or tumors cause cells to exhibit disruption of nuclear membrane integrity during the course of the disease and release dsDNA into the cytoplasm, leading to activation of AIM2 inflammasome." (PMID 39659523, 2024). "The activation of the AIM2 inflammasome consistently occurs concomitantly with the activation of other inflammasomes during viral infections, thus AIM2 inhibitors are anticipated to be used in combination with other agents that modulate the immune response." (PMID 40860203, 2025). "The AIM2 inflammasome has been found to play a significant role in the host's immune response to bacterial and viral infections." (PMID 39744568, 2025). "Nucleic acid sensors (e.g., ZBP1 and AIM2) trigger PANoptosis through mediating the assembly of PANoptosomes during viral infections." (PMID 38932258, 2024). "This study found that in vitro genetic inhibition of AIM2 via siRNA reduced pyroptosis, leading to a significant increase in viral infection suggesting AIM2-mediated pyroptosis is beneficial during EV71 infection." (PMID 39459869, 2024). "Compared to bacterial and viral infection, the role of the AIM2 in response to fungal infection is less clear." (PMID 38918243, 2024). "This review will discuss the recent progress in our understanding of how the AIM2 inflammasome modulates viral infections." (PMID 39459869, 2024). "Second, in addition to ZBP1 and AIM2, can other nucleic acid sensors also act as scaffold proteins for the assembly of PANoptosome during viral infections?" (PMID 38932258, 2024). "In contrast, all mouse PYHIN proteins were dispensable for IFN activation in response to virus infection and DNA ligands, which agrees with minimal STING-dependent activity and an intact interferon-stimulatory DNA (ISD) pathway in AIM2-deficient murine cells." (PMID 38675836, 2024). "As is indicated by its activation mechanism, AIM2 inflammasome is important for protection of the body from viral infection." (PMID 37817895, 2023). "To date, we have only been able to demonstrate that these viral infections induce the expression of AIM2 and its downstream factors, but there are few studies on the specific mechanisms underlying AIM2 activation." (PMID 37608944, 2023). "The dsDNA upstream of AIM2 activation can originate from bacterial infection, viral infection and self‐DNA distributed in cytoplasm." (PMID 37817895, 2023). "We confirmed that the AIM2 expression level increased in the DG after viral infection by RT–PCR and western blotting." (PMID 37177836, 2023). "Production of IL-18 and interferon (IFN)-γ for fighting cytoplasmic viral infections was dependent on AIM2 activation during mCMV infection in mice." (PMID 36298668, 2022). "In particular, upon viral infection, ALR or NLR families, including NLRP1, NLRP2, NLRP3, and AIM2, detect pathogen-associated molecular patterns (PAMPs) and assemble an intracellular inflammasome complex by recruiting ASC and pro-caspase-1." (PMID 34360684, 2021). "The activation of the AIM2 inflammasome has been reported in different viral infections including the HIV." (PMID 34595244, 2021). "The AIM2 inflammasome, a key cytosolic signaling complex activated by double-stranded DNA viruses, was also engaged early after viral infections." (PMID 31367214, 2019). "In infected AIM2-knockdown cells, AIM2 and related downstream gene expressions, and pyroptosis were suppressed, resulting in significantly increased virus infection." (PMID 28724943, 2017). "AIM2 inflammasome activation has previously been shown to occur in response to bacterial and viral infections, but can also be induced by transfection of double-stranded DNA into host cells, bypassing the need for TLRs." (PMID 21698237, 2011). "It is well established that viral infections trigger activation of the AIM2 inflammasome." (PMID 37608944, 2023).
viral infection (continued). "Interestingly, not all DNA viruses can be recognized by AIM2, such as herpes simplex virus 1 (HSV-1), possibly because DNA–AIM2 interaction is inhibited during viral infection." (PMID 32903550, 2020). "AIM2 mediated inflammation had been linked to the pyroptosis during EV-A71 infections as it was up-regulated as well as AIM2 downstream stimulated genes such as CARD16, caspase-1 and IL-1β during viral infection in neuronal cell lines (SK-N-SH)." (PMID 31215493, 2019). "We next asked whether OM-85 was an effective priming agent for multiple activators of the NLRP3 as well as for the AIM2 inflammasome, as both these platforms are important for detection of and protection from viral infections." (PMID 28262817, 2017). "To determine if the increased susceptibility to viral infection of the IL-21R KO mice could be due to an inherent altered expression of PRRs we measured mRNA levels of TLR2, TLR3, TLR9, MDA-5, AIM-2, DAI, RIG-I and IFI16." (PMID 24358128, 2013). "The role of AIM2 in regulating the immune response to viral infection can hereby be emphasized." (PMID 24325587, 2013). "However, AIM2 does not identify all DNA viruses, such as HSV-1, which maybe because viral infection inhibits DNA-AIM2 interactions." (PMID 37465759, 2023). "While various inflammasomes serve to combat a wide array of pathogens, NLRP3 inflammasome, AIM2 inflammasome, and RIG-I inflammasome have been identified as crucial mediators of host responses to viral infection." (PMID 39205246, 2024). "This review illustrates that two main inflammasome sensors have been well studied in the context of viral infection: NLRP3 and AIM2." (PMID 36298668, 2022). "Notably, we performed microarray analysis of microglia (CD45lowCD11b+ cells) isolated from the CNS of WT and AIM2−/− mice of EAE and revealed that the most prominent up-regulated responses in AIM2−/− microglia from EAE-treated mice were associated with defense against viral infection." (PMID 33710283, 2021). "There is growing evidence that inflammasome structures like AIM2 and especially NLRP3 are involved in triggering inflammatory response during virus infection including that of SARS-CoV-2." (PMID 34960782, 2021). "Studies have revealed that NLRP3, AIM2, and IFI16 sensors are pivotal for inflammasome activation in viral infections." (PMID 34595244, 2021). "Several studies have demonstrated that some viruses have the ability to activate diverse inflammasomes, such as the NLRP3, AIM2, and RIG-I inflammasomes, which in turn contributes to mediate the host response to viral infection." (PMID 32324736, 2020). "PYHIN proteins, especially AIM2 and IFI16 are viral infection sensors and activate innate immune response in human cells." (PMID 33584656, 2020). "Another related inflammasome—the AIM2 inflammasome, composed of AIM2, ASC, and Casp1 subunits—was activated by cytosolic DNA during bacterial and viral infection." (PMID 32069862, 2020). "Although less extensively studied in sepsis, other sensors such as AIM2 and IFI16—cytosolic and nuclear DNA detectors, respectively—have emerged as relevant contributors to the host inflammatory response, particularly in the context of viral infections." (PMID 40558557, 2025). "In mice, only 2 main inflammasomes, AIM2 and NLRP3, respond to viral infection." (PMID 40825032, 2025). "During viral infection, the positively charged HIN domain of AIM2 interacts with the negatively charged dsDNA (≥ 80 bp in length) in a sequence-independent manner, through hydrogen bonds at both the major and minor grooves, leading to the formation of AIM2-ASC-caspase-1 inflammasomes." (PMID 40791597, 2025). "Absent in melanoma 2 (AIM2) is an intracellular double-stranded DNA (dsDNA) receptor that senses dsDNA in the cytosol and is a critical host defense mechanism against bacterial and viral infections." (PMID 39352743, 2024). "The DNA sensors AIM2 and IFI16 are able to detect viral DNA upon viral infection." (PMID 39205246, 2024).
viral infection (continued). "It is recommended not to use AIM2 inflammasome inhibitors if there is a clear viral infection, as the AIM2 inflammasome has a protective effect on IFN-I." (PMID 35664004, 2022). "The AIM2 gene is related to the hyperinflammatory manifestation of MIS-C patients since triggers caspase-1 and unleashes pro-inflammatory cytokines such as IL-1β and IL-18,19 which are also involved in the innate immune response to viral infections." (PMID 35770252, 2022). "The main pathways involved in virus infections include the NLRP3, IFI16, and AIM2 pathways." (PMID 34595244, 2021). "Different inflammasomes, including AIM2 and NLRP3, are activated in response to viral infections." (PMID 31479495, 2019). "Of the PRRs, the protein levels of AIM2 increased over time only with viral infection, whereas the levels of IFI16 and NLRP3 showed no remarkable change." (PMID 28369146, 2017). "Of the known inflammasomes, NLRP3, absent in melanoma 2 (AIM2), and IFN inducible protein 16 (IFI16) inflammasomes have been linked to immune responses to intracellular DNA, as well as bacterial and viral infections." (PMID 24109483, 2013). "Instead, early stages of virus infection may activate IFN-I, which in turn leads to AIM2 expression that assists executing phases of innate immunity activation, such as processing and release of pre-synthesized IL-1β, if dsDNA is present in the cytoplasm." (PMID 21994609, 2010). "In addition to cGAS, AIM2, IFI16, and DAI are the cytosolic DNA receptors, activation of which could induce innate immune response to virus infections." (PMID 33664729, 2020). "Upon viral infection of the host, PRRs such as Toll-like receptors (TLRs), nucleotide-binding and oligomerization domain (NOD)-like receptors (NLRs), and intracellular sensors including RIG-I, absent in melanoma 2 (AIM2) and cGAS recognize the viral components." (PMID 39676169, 2024).